SIRT1 (sirtuin 1)
Diseases named in the same sentence as SIRT1 in open-access papers (continued):
Sharing a sentence is not in itself a finding about the gene and the disease.
pancreatic cancer (continued). "In pancreatic cancer, NAM suppressed proliferation, cell cycle progression, invasion, and enhanced apoptosis in vitro by down-regulating SIRT1, KRAS (Kirsten Rat Sarcoma), and p-AKT (phosphated protein kinase B), while it exhibited an analogous effect when administered in combination with valproate." (PMID 32245130, 2020). "Furthermore, inhibition of SIRT1 is effective in suppression of ADM and in reducing cell viability in established pancreatic tumors, where it acts as an independent prognostic factor for survival in patients." (PMID 33042011, 2020). "In a previous study on pancreatic cancer, miR-138-5p is shown to suppress serum starvation-induced autophagy by targeting SIRT1, but not by ATG739." (PMID 31160576, 2019). "miR-217 and SIRT1 play a key role in regulating EMT in chronic pancreatitis and pancreatic cancer." (PMID 30761005, 2019). "Similarly, SIRT1 interacts with Twist and methyl‐CpG binding domain protein‐1 (MBD1) to silence the E‐cadherin promoter in pancreatic cancer." (PMID 28994177, 2017). "Altogether, their results suggested that miR-373 up-regulation and SIRT1 down-regulation induced cell death in pancreatic cancerous cells by suppressing the PGC-1α/ Nrf2 pathway, which could highlight miR-373 as a therapeutic target in pancreatic cancer." (PMID 38970040, 2024). "After observing the antagonistic relationship between BAP1 and SIRT1, particularly in their convergence on the K80 acetylation of HSF1, we became intrigued by the potential efficacy of combining SIRT1 inhibition with ICB therapy in models of pancreatic cancer characterized by BAP1 deletion." (PMID 39350280, 2024). "Therefore, we conclude that due to the acetylation modification of SIRT1 on KIF15, the integrin β1/FAK pathway of KIF15-overexpressed pancreatic cancer cell was activated, providing a prerequisite for the metastasis inhibition effect of EX527 combined with KIF15-IN-1." (PMID 36280663, 2022). "As our studies have shown that the SIRT1/CRL4B complex transcriptionally inhibits GRHL3, we hypothesized that SIRT1 inhibits the differentiation of cancer cells by inhibiting GRHL3 expression, thus promoting the stemness and tumorigenesis of pancreatic cancer." (PMID 34163012, 2021). "In the present study, we used pancreatic cancer cell lines in vitro, an in vivo tumor mouse model, and pancreatic cancer patient tissue samples to identify a novel SYT8-dependent molecular mechanism mediating pancreatic cancer cell proliferation and invasion via TNNI2, ERRα, and SIRT1." (PMID 34907162, 2021). "However, neither SIRT1 nor PARP-1 (another NAD+ dependent enzyme) play a significant role on the effect of NAMPT inhibition on pancreatic cancer cells." (PMID 33042011, 2020). "Moreover, when examining noncancerous and pancreatic cancer tissues, SIRT1 was significantly overexpressed in the former specimens compared with the pancreatic cancer tissues." (PMID 28052003, 2017). "SIRT1 or CUL4B knockdown in PANC-1 cells decreased cell invasion potential, which was partially rescued via the co-knockdown of FOXO3 or GRHL3, indicating that the SIRT1/CRL4B complex could promote pancreatic cancer invasion through repression of FOXO3 and GRHL3." (PMID 34163012, 2021). "Although not UES in PharmacoDB, inhibition of the HST1 homolog, SIRT1, by Tenovin-6 inhibits the growth of acute lymphoblastic leukemia cells and enhances cytarabine cytotoxicity, enhances gemcitabine efficacy in pancreatic cancer cell lines, and improves survival in a pancreatic cancer mouse model." (PMID 31575041, 2019).
myocardial ischemia (78 papers, 2014 to 2026). A disorder of cardiac function caused by insufficient blood flow to the muscle tissue of the heart. "Xinmai’an tablets deduce mitochondrial oxidative stress damage by activating the AMPK/SIRT1/PGC-1α pathway to alleviate myocardial ischemia/reperfusion injury." (PMID 40533778, 2025). "The protective effects of EGCG were blocked by SIRT1 inhibitors or siRNA, indicating that EGCG alleviates myocardial ischemia/reperfusion (I/R) injury in diabetic rats by activating the SIRT1 signaling pathway and upregulating MnSOD expression." (PMID 40746722, 2025). "Previous work by our group has reported that BBR improves myocardial ischemia reperfusion injury by reducing oxidative stress and inflammation response in a SIRT1‐dependent manner." (PMID 38894630, 2024). "Studies have shown that CAPE ameliorates myocardial ischemia/reperfusion injury by suppressing oxidative stress and the inflammatory response through the SIRT1/eNOS/NF-κB pathway." (PMID 38528569, 2024). "The present study revealed that the sirtuin 1 contributes to syringin‐mediated protection against myocardial ischemia/reperfusion in rats." (PMID 36840496, 2023). "It was found that antioxidant treatment can restore Sirt1 repression and rescue the cardiac ischemia-sensitive phenotype induced by GDM." (PMID 37571325, 2023). "SIRT1 upregulated the downstream signaling pathway of Nrf2 by reducing the acetylation level of Nrf2, thereby improving myocardial ischemia/reperfusion injury." (PMID 36937895, 2023). "Lumbrokinase treatment has also been reported to reduce oxidative damage, inflammation, and apoptosis induced by myocardial ischemia–reperfusion (I–R) through the activation of Sirt1 signaling." (PMID 37627791, 2023). "For example, SIRT1 stabilizes atherosclerotic plague and prevents cardiac ischemia and hypertrophy during aging, protecting cardiomyocytes." (PMID 36359987, 2022). "XFZYD was also shown to protect myocardial ischemia rats via the SIRT1-mediated signal transduction pathway." (PMID 35186096, 2022). "Treatment with curcumin at doses of 2.71 and 54.3 μM, activates the expression of SIRT1, which is known to significantly suppress the mitochondrial oxidative damage in myocardial ischemia-reperfusion injury." (PMID 36143462, 2022). "RSV increased phosphorylation of FOXO1 through phosphorylation of AMPK and SIRT1, thereby reducing ROS and apoptosis level to alleviate myocardial ischemia–reperfusion injury." (PMID 35791579, 2022). "Increasing evidence shows that SIRT1 is related to cellular hypoxia and heart protection from endoplasmic reticulum stress-related organ damage, ageing, myocardial ischemia, and hypertrophy." (PMID 36363464, 2022). "In animal models, quercetin improves myocardial ischemia/reperfusion (I/R)-induced cardiomyocyte apoptosis via SIRT1/peroxisome proliferator-activated receptor gamma coactivator-1 alpha (PGC-1α) signalling." (PMID 36225565, 2022). "Puerarin inhibits inflammation by activating SIRT1/NF-κβ signaling pathway, improving myocardial ischemia-reperfusion injury." (PMID 35482440, 2022). "The SIRT1/Nrf2 pathway was also activated by crocin and mediated alleviation of myocardial ischemia/reperfusion-induced injury." (PMID 35655597, 2022). "In mice with myocardial ischemia/reperfusion injury, upregulation of miR-155 increases infarction size and myocardial cell apoptosis via targeting SIRT1." (PMID 33748285, 2021). "In terms of oxidative stress, resveratrol can reduce myocardial oxidative stress by stimulating Sirtuin1 (SIRT1) or inhibiting GSK3β in diabetic cardiac ischemia-reperfusion injury models and increasing nuclear factor E2-related factor 2 (Nrf2) expression." (PMID 34093716, 2021). "In cerebral and myocardial ischemia, the same mode of action of arctigenin has been reported, through activation of SIRT1 signaling pathway." (PMID 34942997, 2021).
myocardial ischemia (continued). "Myocardial ischemia and HCM share the following elements: calcium, ATP, AMPK, PKA, AKT cross-talking with ERK, glucose, INS, SIRT1 gene encoding sirtuin 1, NF-κB, TNF, reactive oxygen species, inflammatory response, and apoptosis." (PMID 34440529, 2021). "Li D and others discovered that caffeic acid phenylethyl ester (CAPE) inhibit the NF-κB signaling by promoting SIRT1/eNOS expression, thus inhibiting oxidative stress, inflammation, fibrosis, and necrosis and improve the rat myocardial ischemia damage." (PMID 33574759, 2020). "Overexpression of SIRT1 reduced myocardial ischemia/reperfusion (MI/R) injury in the heart, while cardiac specific downregulation of SIRT1 promoted myocardial injury following MI/R." (PMID 26489513, 2015). "However, the translational potential of these findings and the optimal strategies for targeting SIRT1 in the context of myocardial ischemia-reperfusion injury remain to be determined." (PMID 38745862, 2024). "First, Sal B can further induce NLRP3 inactivation by inhibiting intracellular ROS production during myocardial ischemia, increasing the mitochondrial membrane potential, regulating the expression levels of SIRT1, Parkin, and PINK1 proteins, and promoting mitochondrial autophagy." (PMID 39323645, 2024). "SIRT1 overexpression protects against myocardial ischemia-reperfusion injury." (PMID 39857372, 2024). "Moreover, it has been reported that SIRT1 overexpression increased nuclear factor E2-related factor 2 (Nrf2) deacetylation and its activity in a myocardial ischemia/reperfusion injury mouse model." (PMID 38397799, 2024). "Furthermore, MLN4924 exhibited strong cardioprotective effects against myocardial ischemia/reperfusion (MI/R) via induced autophagic flux and up-regulated Nrf2 mediated by SIRT1." (PMID 38398217, 2024). "Furthermore, downregulation of sirtuin 1 (Sirt1), a protective factor against cardiovascular diseases such as myocardial ischemia, has been observed in adult male offspring of mothers with GDM." (PMID 37571325, 2023). "The dynamic network of SIRT1/SIRT3 in response to myocardial ischemia and reperfusion stress." (PMID 37537789, 2023). "Besides, the regulation of general autophagy by Sirt1 is well-known, and there is evidence that Sirt1 plays a protective role in cardiac ischemia-reperfusion and bone metabolism disorders through PINK1/Parkin-mediated mitophagy." (PMID 36312244, 2022). "As a ROS scavenger, it improved pancreatic β-cell function by attenuating oxidative stress through Nrf2/ARE pathway in diabetic rats and ameliorated diabetic myocardial ischemia/reperfusion (MI/R) injury by reducing oxidative stress by activating the SIRT1-Nrf2 signaling pathway." (PMID 36466390, 2022). "Recently, we have determined the critical role of SIRT1 in mediating protective effect of natural products to reduce damages in both simple myocardial ischemia/reperfusion and ischemia/reperfusion with type 1 diabetes by attenuating oxidative stress and apoptosis." (PMID 31210844, 2019). "Importantly, Sirt1 is thought to play a crucial role in cardioprotection against myocardial ischemia/reperfusion injury through sumoylation which in turn induces lysine deacetylation of cytosolic proteins." (PMID 29872406, 2018).
myocardial ischemia (continued). "Here, we hypothesized that resveratrol may protect against myocardial ischemia/reperfusion injury (MIRI) through the target of Sirt1/Sirt3 on mitochondrial dynamics, cardiac autophagy, bioenergetics and oxidative damage in hypoxia/reoxygenation (H/R)-induced neonatal rat cardiomyocytes." (PMID 36080311, 2022). "Moreover, OIP5-AS1 could activate the SIRT1/AMPK/PGC1α pathway by sponging miR-29a to attenuate myocardial ischemia/reperfusion injury." (PMID 34631806, 2021). "Because of experimental limitations, we chose only the SIRT1/MAPK pathway and apoptosis mechanism to verify the effects of Sal-B in the treatment of myocardial ischemia-reperfusion, ignoring other pathways and targets." (PMID 38543095, 2024). "Our lab previously reported that the protein expression level of SIRT1 reduces with aging in hearts and its activity is also limited due to the reduction of NAD+ level in aged hearts during myocardial ischemia stress." (PMID 37537789, 2023). "Age‐related sensors Sirtuin1 (SIRT1) and Sirtuin3 (SIRT3) play an essential role in the protective response upon myocardial ischemia and/or reperfusion (I/R)." (PMID 37537789, 2023). "A previous study showed that tilianin pretreatment improved mitochondrial energy metabolism and decreased oxidative stress through the AMPK/SIRT1/PGC-1α signaling pathway, thus attenuating myocardial ischemia/reperfusion injury." (PMID 35812724, 2022). "From in vivo studies of myocardial ischemia, arctigenin seemed to activate AMPK/SIRT1 signaling pathway, and consequently an upregulation of I-κB and inhibition of NF-κB have been observed." (PMID 34942997, 2021). "Another study reported that punicalagin inhibits NF-κB nuclear translocation by activating the SIRT1-mediated NRF-2-HO-1 signaling pathway, thereby relieving myocardial ischemia/reperfusion injury-induced cardiac oxidative stress and inflammation." (PMID 33574759, 2020). "Silent information regulator l (SIRT1), which acts as the regulator of mitochondrial biogenesis, was significantly enhanced by DATS in myocardial ischemia–reperfusion (MI/R) injury models." (PMID 32283691, 2020). "Moreover, in vitro experiments used to mimic myocardial ischemia and reperfusion injury related ANRIL downregulation with miR-181a/SIRT1 regulation." (PMID 38771854, 2024). "In mice subjected to myocardial ischemia‐reperfusion, the CD36 ligand azapeptide CP‐3(iv), increased circulating adiponectin levels, epididymal fat adiponectin gene expression, and transcriptional regulators (Pparg, Cebpb, Sirt1) after 6 h of reperfusion." (PMID 39552437, 2024). "In addition, SIRT1 can be regulated by Tan IIA to inhibit the inflammatory response, to relieve the myocardial ischemia reperfusion injury, and to treat mast cell-mediated allergic diseases." (PMID 36670462, 2023). "It is known that SIRT1 can inhibit the expression levels of p65, TNF-α, IL-1β, IL-6, iNOS, and other markers related to oxidative stress by regulating the NF-κB pathway, thus playing a role in myocardial ischemia-reperfusion." (PMID 34868528, 2021). "In addition, NMN activates autophagy during myocardial ischemia, which is consistent with the finding that NAMPT and SIRT1 promote autophagy in cardiomyocytes." (PMID 32411700, 2020). "Notably, ROS and SIRT1/SIRT3 are major regulators of substrate metabolism, which modulates the inflammatory responses during myocardial ischemia and reperfusion." (PMID 32933202, 2020). "This feature may be also considered an important tool in hypothermia-related death in forensics, in opposition to death due to myocardial ischemia or infarction, characterised by a lack of SIRT1 expression in modified myocardial tissue, in agreement with our results." (PMID 36363464, 2022).
myocardial ischemia (continued). "Notably, NMN attenuated the increase in acetylation of FoxO1 during myocardial ischemia, but NMN failed to reduce the infarct size in Sirt1-KO mice, indicating that the protective effect of NMN on the heart following I/R injury is partly mediated by Sirt1." (PMID 32411700, 2020).
Stroke (78 papers, 2011 to 2025). Sudden impairment of blood flow to a part of the brain due to occlusion or rupture of an artery to the brain. "Several earlier reports have linked sirtuins, specifically SIRT1, to stroke and autophagy, reinforcing the importance of this connection in stroke pathogenesis." (PMID 40724883, 2025). "Increased levels of SIRT1 during brain repair after stroke were associated with an increase in synaptic plasticity proteins, one of the key mechanisms by which the brain recovers its function after injury." (PMID 40356977, 2025). "In a word, Sirt1 mediated the synthesis of triglyceride and inhibition of neuronal apoptosis after stroke, which was associated with the QKI 6 and the PPARγ/PGC-1α signaling pathway." (PMID 37622049, 2023). "SIRT1 overexpression is protective in adult stroke models, while SIRT1-deficient mice display larger infarct volume after permanent middle cerebral artery occlusion (MCAO)." (PMID 37787108, 2023). "The loss of SirT1 function in post‐stroke muscle is primarily responsible for the activation of UPS at least through elevating Atrogin‐1, MuRF1, and ZNF216 gene expressions." (PMID 32676579, 2020). "A SIRT1-dependent increase in Bcl2 has also been reported in a stroke context after curcumin pretreatment and has been linked to anti-inflammatory properties." (PMID 33519368, 2020). "SIRT1 has been proposed to mediate neuron survival based on its broad deacetylase activity and has been linked to a positive stroke outcome." (PMID 21910904, 2011). "In brief, Sirt1 exhibits promising potential as a therapeutic target for ischemic stroke and plays a vital role in reducing the neuropathology associated with this condition, minimizing brain injury, and enhancing stroke prognosis." (PMID 40160465, 2025). "Therefore, SIRT1 can be upregulated in stroke alongside genes encoding essential autophagy proteins and caspase-3, which is important in apoptosis." (PMID 40724883, 2025). "In addition, Sirt1 increases the activity of DNA repair pathways such as the poly [ADP-ribose] polymerase 1 (PARP1) pathway associated with stroke." (PMID 36076942, 2022). "Collectively, these studies suggest that the loss of SirT1 function in post‐stroke muscle is likely due to overactivation of PARP‐1 that could have utilized most of the available intracellular NAD+ needed for SirT1 activity." (PMID 32676579, 2020). "In the current study, stroke represses SirT1 activity and that loss of SirT1 function may increase the activity of PARP‐1 in post‐stroke muscle." (PMID 32676579, 2020). "Additionally, the results may provide a base for our future study regarding the regulation of SIRT1 on the ROS/ER stress pathway in the biochemical processes underlying post-stroke neuroprotection." (PMID 33664650, 2021). "Meanwhile, edaravone treatment has been shown to activate Nrf2, heme oxygenase 1, and SIRT1 in experimental models of traumatic brain injury, amyotrophic lateral sclerosis, and stroke." (PMID 40260386, 2025). "An increased expression of SIRT1 was observed in a rat MCAO model of stroke that was intraarterially infused with MSCs." (PMID 40724883, 2025). "Exercise intervention reduces post-stroke depression-like behavior by activating SIRT1/BDNF/mTORC1 signaling pathway and reducing neuroinflammation." (PMID 40071363, 2025). "Pharmacological inhibition of ACMSD amplifies NAD+ synthesis, restoring redox balance and enhancing sirtuin-1-mediated synaptic plasticity essential for post-stroke memory consolidation and emotional regulation." (PMID 41184254, 2025). "The stroke insult-related genes were Nfkb1, histone deacetylase 2 (Hdac2), and sirtuin 1 (Sirt1) in the vs. MCAO+tDCS-FN(cA) and U2 small nuclear RNA auxiliary factor 2 (U2af2) in the vs. MCAO+tDCS-FN(iC-cA) configurations." (PMID 38389833, 2024). "Resveratrol effects multiple pathways, including SIRT1, Nrf2, and Shh which overall lead to reduced inflammation, oxidative stress, and better stroke outcomes." (PMID 39082038, 2024).